CAPNS2 (calpain small subunit 2)
Description:
Calcium-regulated non-lysosomal thiol-protease which catalyzes limited proteolysis of substrates involved in cytoskeletal remodeling and signal transduction. This small subunit may act as a tissue-specific chaperone of the large subunit, possibly by helping it fold into its correct conformation for activity.
Synonyms: CSS2; MGC12536; MGC14804
Tractability: Antibody: its Gene Ontology location is reachable by antibodies, with high confidence; UniProt places it where antibodies can reach, with medium confidence. PROTAC: ubiquitination databases record sites on it.
Gene: Protein-coding gene on chromosome 16 (55,566,684 to 55,567,687, forward strand). Ensembl gene ENSG00000256812.
Subcellular location: Cytoplasm; Cell membrane
Subcellular location (Human Protein Atlas): Cytosol
Pathways (Reactome):
Cellular responses to stimuli: High laminar flow shear stress activates signaling by PIEZO1 and PECAM1:CDH5:KDR in endothelial cells; Turbulent (oscillatory, disturbed) flow shear stress activates signaling by PIEZO1 and integrins in endothelial cells
Disease: Deregulated CDK5 triggers multiple neurodegenerative pathways in Alzheimer's disease models
Extracellular matrix organization: Degradation of the extracellular matrix
Gene Ontology:
Molecular function: calcium-dependent cysteine-type endopeptidase activity; protein binding; calcium ion binding
Cellular component: calpain complex; cytosol; plasma membrane; cytoplasm
Genetic constraint (gnomAD): Loss-of-function variants: 13 observed, 18.56 expected, observed/expected ratio (o/e) 0.7, 90% interval 0.46 to 1.11. The upper end of that interval is the gene's LOEUF score, 1.11, which puts it in group 4 of 6, group 1 being the genes least tolerant of losing a copy. Missense variants: 279 observed, 317.78 expected, observed/expected ratio (o/e) 0.88, 90% interval 0.8 to 0.97. Synonymous variants: 101 observed, 114.05 expected, observed/expected ratio (o/e) 0.89, 90% interval 0.75 to 1.04.
Homologues: Orthologues: mouse Capns2 (92% identical), Drosophila melanogaster CalpB (32% identical), zebrafish zgc:85932 (26% identical), zebrafish capn12 (25% identical), tropical clawed frog capn12 (24% identical), Caenorhabditis elegans clp-8 (19% identical), Drosophila melanogaster Pef (13% identical), Caenorhabditis elegans tra-3 (12% identical), Caenorhabditis elegans clp-3 (8% identical), Caenorhabditis elegans clp-1 (7% identical), Caenorhabditis elegans clp-7 (7% identical), Caenorhabditis elegans clp-6 (6% identical), and 2 more. Paralogues in human: CAPNS1 (68% identical), CAPN3 (44% identical), CAPN1 (42% identical), CAPN2 (38% identical), CAPN11 (38% identical), CAPN9 (38% identical), CAPN8 (37% identical), CAPN12 (30% identical), CAPN14 (29% identical), CAPN13 (27% identical), ADGB (20% identical), CAPN5 (19% identical), and 8 more.
Diseases named in the same sentence as CAPNS2 in open-access papers:
CAPNS2 is named in the same sentence as 3 diseases in open-access papers, as found by Europe PMC text mining. Sharing a sentence is not in itself a finding about the gene and the disease. The quoted sentences say what the papers report.
Schinzel-Giedion syndrome (1 paper, 2016). Schinzel-Giedion syndrome (SGS) is an ectodermal dysplasia syndrome chiefly characterized by a distinctive facial dysmorphism, hydronephrosis, severe developmental delay, typical skeletal malformations, and genital and cardiac anomalies. "On the blood side of this signature were among others the PPP2R2B gene associated with SCA12, CAPNS2, which was recently found to play a beneficial role against polyglutamine toxicity, and SETBP1 which is associated with the Schinzel-Giedion syndrome." (PMID 27476530, 2016).
CAPNS2 also shares sentences with these, for which no sentence is quoted: cancer (1 paper); tumor (1).